MAPK6 (mitogen-activated protein kinase 6)
Description:
Atypical MAPK protein. Phosphorylates microtubule-associated protein 2 (MAP2) and MAPKAPK5. The precise role of the complex formed with MAPKAPK5 is still unclear, but the complex follows a complex set of phosphorylation events: upon interaction with atypical MAPKAPK5, ERK3/MAPK6 is phosphorylated at Ser-189 and then mediates phosphorylation and activation of MAPKAPK5, which in turn phosphorylates ERK3/MAPK6. May promote entry in the cell cycle (By similarity).
Synonyms: ERK3; PRKM6; p97MAPK; HsT17250
Tractability: Small molecule: a structure with a bound ligand is known; a high-quality ligand is known; it has a high-quality binding pocket; it belongs to a druggable protein family. PROTAC: it is named in the literature on targeted protein degradation; UniProt records ubiquitination sites on it; ubiquitination databases record sites on it; a small molecule that binds it is known.
Target class: CMGC protein kinase group; CMGC protein kinase ERK3; Enzyme; CMGC protein kinase MAPK family; Kinase; Protein Kinase
Gene: Protein-coding gene on chromosome 15 (51,952,106 to 52,067,375, forward strand). Ensembl gene ENSG00000069956.
Subcellular location: Cytoplasm; Nucleus
Subcellular location (Human Protein Atlas): Cytosol; Microtubules; Primary cilium
Pathways (Reactome):
Signal Transduction: MAPK6/MAPK4 signaling
Gene Ontology:
Molecular function: protein binding; MAP kinase activity; protein serine/threonine kinase activity; ATP binding; protein heterodimerization activity; protein kinase activity; protein kinase binding; protein serine kinase activity
Biological process: intracellular signal transduction; protein phosphorylation; signal transduction; MAPK cascade
Cellular component: cytoplasm; cytosol; nucleoplasm; nucleus; protein-containing complex; septin cytoskeleton
Genetic constraint (gnomAD): Loss-of-function variants: 18 observed, 57.44 expected, observed/expected ratio (o/e) 0.31, 90% interval 0.22 to 0.47. The upper end of that interval is the gene's LOEUF score, 0.47, which puts it in group 2 of 6, group 1 being the genes least tolerant of losing a copy. Missense variants: 716 observed, 850.88 expected, observed/expected ratio (o/e) 0.84, 90% interval 0.79 to 0.89. Synonymous variants: 313 observed, 295.61 expected, observed/expected ratio (o/e) 1.06, 90% interval 0.96 to 1.16.
Homologues: Orthologues: chimpanzee MAPK6 (100% identical), macaque MAPK6 (99% identical), dog MAPK6 (98% identical), rabbit MAPK6 (98% identical), pig MAPK6 (98% identical), mouse Mapk6 (95% identical), rat Mapk6 (94% identical), guinea pig MAPK6 (88% identical), tropical clawed frog mapk6 (86% identical), zebrafish mapk6 (76% identical), Caenorhabditis elegans pmk-2 (17% identical), Caenorhabditis elegans pmk-1 (17% identical), and 7 more. Paralogues in human: MAPK4 (44% identical), MAPK7 (25% identical), MAPK1 (22% identical), MAPK3 (21% identical), CILK1 (19% identical), NLK (19% identical), MAPK15 (19% identical), MAK (18% identical), MAPK13 (18% identical), MAPK12 (17% identical), MAPK14 (17% identical), MAPK8 (17% identical), and 7 more.
Diseases named in the same sentence as MAPK6 in open-access papers:
MAPK6 is named in the same sentence as 50 diseases in open-access papers, as found by Europe PMC text mining. Sharing a sentence is not in itself a finding about the gene and the disease. The quoted sentences say what the papers report.
breast carcinoma (9 papers, 2020 to 2025). "MAPK6 overexpression is associated with decreased overall survival and the survival of patients with lung adenocarcinoma, mesothelioma, uveal melanoma, and breast cancer." (PMID 34767444, 2021). "Existing evidence indicates that circ_0015278 inhibits breast cancer progression by targeting MAPK6 and regulates the PI3K/AKT axis to impede gastric cancer progression." (PMID 39866239, 2025). "Herein, we aimed to investigate the anticancer effects of MAPK6 knockdown by using MAPK6 siRNA‐loaded PLGA nanoparticles (siMAPK6‐PLGA‐NPs) in MCF‐7 breast cancer cells." (PMID 39823246, 2025). "MAPK6 is upregulated in breast cancer and is involved in cell growth, differentiation and cell cycle regulation." (PMID 39823246, 2025). "For example, circRNA_100395 acts as a microRNA sponge in breast cancer pathogenesis to suppress overexpression of the gene MAPK6, inhibiting the proliferation and expansion of breast cancer cells." (PMID 37561093, 2023). "Our findings demonstrated that siRNA‐loaded PLGA nanoparticles have great potential for breast cancer treatment and MAPK6 gene may be the therapeutic target in breast cancer." (PMID 39823246, 2025). "In the present study, MAPK6 was identified as a therapeutic target in MCF‐7 breast cancer cells." (PMID 39823246, 2025). "While MAPK6 has not been directly implicated in glioma, it promotes tumor growth in several other tumor types, including lung adenocarcinoma, mesothelioma, uveal melanoma, and breast cancer." (PMID 42135822, 2025). "miR-26a-5p/ULK1 and miR-26a-5p/MAPK6 axis were also regulated by SNHG6 and participated in the development and progression of breast cancer and osteosarcoma, respectively." (PMID 32655318, 2020). "Accordingly, knockdown of MAPK6 in four cancer cell lines with medium to high expression of endogenous MAPK6 (MCF7 and SUM159 for breast cancer, PC3 for prostate cancer, and H1299 for non–small cell lung cancer) inhibited cell growth in vitro and/or xenograft growth in vivo." (PMID 34767444, 2021). "To critically examine how MAPK6 regulates human cancers, we used six common human cancer cell lines representing four different cancer types, including prostate cancer (PC3 and DU145), breast cancer (MCF7 and SUM159), ovarian cancer (OVCA433), and non–small cell lung cancer (H1299)." (PMID 34767444, 2021). "The pro-oncogenic role of MAPK6 described here is also strongly supported by the observation that elevated MAPK6 mRNA expression negatively correlates with pan-cancer patient survival and survival in specific cancer types, including LUAD, MESO, UVM, and breast cancer." (PMID 34767444, 2021).
cervical cancer (7 papers, 2021 to 2025). A primary or metastatic malignant neoplasm involving the cervix. "Additionally, Rab31 inhibited the degradation of MAPK6, and MAPK6 overexpression restored the reduced invasion capability of cervical cancer cells caused by Rab31 knockdown." (PMID 34975321, 2022). "have demonstrated that knockdown of MAPK6 inhibited the proliferation, migration, and invasion of cervical cancer cells." (PMID 39823246, 2025). "We conclude from these results that the pro-invasive effect of Rab31 in cervical cancer is partially dependent on MAPK6." (PMID 34975321, 2022). "In conclusion, Rab31 plays a crucial role in cervical cancer metastasis by inhibiting MAPK6 degradation." (PMID 34975321, 2022). "We showed that MAPK6 overexpression partially restored the migration potential of Rab31-knockdown cervical cancer cells." (PMID 34975321, 2022). "MAPK6 also promoted cervical cancer cell growth, but inhibited melanoma and intrahepatic cholangiocarcinoma cell proliferation." (PMID 34767444, 2021). "Furthermore, another article has elucidated that the knockdown of MAPK6 suppresses cervical cancer cell proliferation, migration, and invasion." (PMID 36895010, 2023). "Transwell assay showed that MAPK6 knockdown inhibited cervical cancer cell migration and invasion." (PMID 34975321, 2022). "We also investigated whether MAPK6 affected the development of cervical cancer and showed that MAPK6 knockdown inhibited the viability, migration and invasion of cervical cancer cells as well as Rab31-overexpressing cells." (PMID 34975321, 2022). "We performed rescue experiments to further determine whether Rab31 promoted the invasion of cervical cancer cells in a MAPK6-dependent manner." (PMID 34975321, 2022). "In addition to MAPK6, other molecules or pathways may be responsible for Rab31-mediated migration and invasion of cervical cancer cells." (PMID 34975321, 2022). "Finally, MiR-144-3p inhibits cervical cancer growth by specifically targeting MAPK6." (PMID 35501800, 2022). "Rab31 is overexpressed in cervical cancer tissues and enhances migration and invasion of cervical cancer cells by promoting epithelial mesenchymal transition (EMT) and affects the cytoskeletal rearrangement in an MAPK6-dependent manner." (PMID 38695990, 2024). "MAPK6 also promoted HUVEC, VSMC, and cervical cancer cell growth." (PMID 34767444, 2021).
lung carcinoma (5 papers, 2020 to 2025). "For example, MAPK6 is highly expressed in human lung carcinomas and promotes the invasion of lung cancer cells." (PMID 34975321, 2022). "have revealed that MAPK6 is upregulated in lung cancer and knockdown of MAPK6 inhibited invasion." (PMID 39823246, 2025). "have demonstrated that MAPK6 is upregulated in non‐small cell lung cancer." (PMID 39823246, 2025). "We further assessed MAPK6 protein expression in a human lung cancer tissue microarray (TMA) consisting of n = 102 matched normal and cancer tissues from the Xiangya Hospital of Central South University, China (n = 50 LUAD, n = 49 squamous cell lung cancer, and n = 3 adenosquamous carcinoma)." (PMID 34767444, 2021). "Last, we observed that MAPK6 protein expression correlated with AKT phosphorylation in both a pan-cancer (Baylor) cohort and a lung cancer [Central South University, China (CSU)] cohort." (PMID 34767444, 2021). "MAPK6, also known as ERK3, were found to be strongly upregulated in human lung carcinoma and promotes cancer cell invasion." (PMID 33273537, 2020).
lung squamous cell carcinoma (5 papers, 2021 to 2025). "Recently, LINC00649 has been revealed to interact with TAF15 to facilitate the progression of lung squamous cell carcinoma by enhancing MAPK6 expression and activating the MAPK signaling pathway." (PMID 36895010, 2023). "Recently, it has been reported that TAF15 affects MAPK6 expression by stabilizing MAPK6 mRNA in lung squamous cell carcinoma (LUSC) cells." (PMID 36895010, 2023). "For instance, a study unveiled the involvement of LINC00649 in recruiting TAF15 to stabilize MAPK6 expression, thereby promoting the progression of lung squamous cell carcinoma through activation of the mitogen-activated protein kinase (MAPK) signaling pathway." (PMID 39735666, 2025). "LINC00649 was revealed to recruit TAF15, an element stabilizing the expression of mitogen-activated protein kinase 6 (MAPK6), thus activating the MAPK signaling pathway in lung squamous cell carcinoma." (PMID 37504305, 2023).
lung adenocarcinoma (4 papers, 2018 to 2025). A carcinoma that arises from the lung and is characterized by the presence of malignant glandular epithelial cells. "In this research, we discovered that a transcript factor, hepatocyte nuclear factor 4 gamma (HNF4G), significantly increases cisplatin’s resistance in lung adenocarcinoma by upregulating the MAPK6/Akt signaling pathway." (PMID 36923501, 2023). "HNF4G promotes MAPK6 expression and subsequent Akt phosphorylation by binding to the MAPK6 promoter region, resulting in resistance to cisplatin in lung adenocarcinoma." (PMID 36923501, 2023). "Our findings also confirmed that HNF4G promotes the Akt signaling pathway, and we further revealed that HNF4G activates the Akt signaling pathway in lung adenocarcinoma by increasing MAPK6 expression." (PMID 36923501, 2023). "Meanwhile, the RNA-Seq data from the TCGA database revealed that the expression of HNF4G was significantly positively correlated with the expression of MAPK6 in patients with lung adenocarcinoma, also indicating that HNF4G regulates the expression of MAPK6." (PMID 36923501, 2023). "By binding to the MAPK6 promoter region, HNF4G promotes MAPK6 expression and subsequent Akt phosphorylation, resulting in resistance to cisplatin in lung adenocarcinoma." (PMID 36923501, 2023). "Based on the findings, we first discovered that HNF4G promotes MAPK6 expression and subsequent Akt phosphorylation by binding to the MAPK6 promoter region, resulting in cisplatin resistance in lung adenocarcinoma." (PMID 36923501, 2023). "Our primary screen generated a functionally annotated list of 28 genes that led to robust metastatic dissemination and merit further interrogation, including some that have been previously identified to be mutated in lung adenocarcinoma (GNAS, MAPK6, ACVR1B, FBXW7, NTRK3)." (PMID 30013058, 2018).
renal fibrosis (4 papers, 2022 to 2025). A final common manifestation of a wide variety of chronic kidney diseases characterized by glomerulosclerosis and tubulointerstitial fibrosis. "The results indicated that exosomal miR-374a-5p prevented the progression of renal fibrosis by regulating MAPK6/MK5/YAP axis for the first time." (PMID 35137672, 2022). "In conclusion, exosomal miR-374a-5p inhibited the progression of renal fibrosis by regulating MAPK6/MK5/YAP axis." (PMID 35137672, 2022). "In conclusion, exosomes from miR-374a-5p-modified MSCs prevented the progression of renal fibrosis by regulating MAPK6/MK5/YAP axis." (PMID 35137672, 2022). "For example, we only confirmed the relationship between miR-374a-5p and MAPK6 in the pathological process of renal fibrosis." (PMID 35137672, 2022). "Furthermore, miR-374a-5p has been shown to impede the progression of renal fibrosis by modulating the MAPK6/MK5/YAP axis, ultimately leading to reductions in urea and creatinine levels." (PMID 40524833, 2025). "All in all, MSC/miR-374a-5p-Exo could inhibit the progression of renal fibrosis in vivo by regulating MAPK6/MK5/YAP axis." (PMID 35137672, 2022). "Furthermore, exosomal miR-374a-5p prevented the progression of renal fibrosis in vivo by regulating MAPK6/MK5/YAP axis." (PMID 35137672, 2022). "Moreover, the current studies have found that MAPK6/MK5/YAP axis was involved in the process of renal fibrosis inhibited by miR-374a-5p modified exosomes, and it is worth exploring whether other axes are also involved." (PMID 35137672, 2022). "Current data had concluded that MSC/miR-374a-5p-Exo markedly inhibited TGF-β1-induced apoptosis of HK-2 cells and prevented the progression of renal fibrosis in vivo by regulating MAPK6/MK5/YAP axis, suggesting that MAPK6/MK5/YAP was vital in the pathogenesis of renal fibrosis." (PMID 35137672, 2022).
diabetic nephropathy (3 papers, 2022 to 2025). "circ_0000285 promotes diabetic nephropathy progression via miR-654-3p suppression and MAPK6 activation." (PMID 41009556, 2025). "Furthermore, circRNA_0000285 induced damage to podocytes by targeting miR-654-3p and regulating mitogen-activated protein kinase 6 (MAPK6) in diabetic nephropathy." (PMID 35166172, 2022). "For instant, high expression of MAPK6 in diabetic nephropathy could induce podocyte injury." (PMID 35137672, 2022).
Alzheimer disease (2 papers, 2023 to 2024). A progressive, neurodegenerative disease characterized by loss of function and death of nerve cells in several areas of the brain leading to loss of cognitive function such as memory and language. "MEG3 (ENST00000398461)/hsa-let-7d-5p/ATF6B axis showed importance in Parkinson’s and late Alzheimer’s diseases, while AC092687.3/hsa-let-7e-5p/[SREBF2, FNIP1, PMAIP1] and SDCBP2-AS1 (ENST00000446423)/hsa-miR-101-3p/MAPK6 axes are probably related to Alzheimer’s disease development and pathology." (PMID 38027526, 2023).
laryngeal carcinoma (2 papers, 2023 to 2024). Carcinoma that arises from the laryngeal epithelium. "In an example of negative regulation, ZNF671 reduced MAPK6 promoter activity and ERK3 level in the laryngeal carcinoma cell lines AMC-HN-8 and TU177." (PMID 38611058, 2024).
mastitis (2 papers, 2021 to 2022). Inflammation of breast tissue during lactation or postpartum due to an obstructed duct or infection. "Of the 12 co-expressed down-regulated genes, TFRC and MAPK6 are thought to be associated with immunity and mastitis, LARP1B and ODC1 are associated with reproductive traits, such as oestrogen and sperm quality." (PMID 35480317, 2022). "RAB5C and MAPK6 genes were identified as candidate genes for mastitis in dairy cattle following intramammary infection with E. coli or S. uberis using a combination of GWAS and DEG data analyses." (PMID 34691146, 2021).
melanoma (2 papers, 2021 to 2023). A malignant, usually aggressive tumor composed of atypical, neoplastic melanocytes. "In contrast, MAPK6 was reported to repress fibroblast cell cycle progression, melanoma and intrahepatic cholangiocarcinoma cell proliferation, and melanoma cell migration, all of which support a tumor suppressor function." (PMID 34767444, 2021). "A recent study shows that MAPK6/ERK3 exerts its tumor suppressor function by inhibiting cell cycle progression and proliferation and invasion of melanoma." (PMID 38283944, 2023).
oral squamous cell carcinoma (2 papers, 2021). "Among the target genes, Fhl2 was reported to contribute to tongue squamous cell carcinoma and other cancers; Mapk6 is a Ser/Thr protein kinase and is related with oral squamous cell carcinoma and other cancers." (PMID 34409068, 2021).
ameloblastoma (1 paper, 2022). The most common odontogenic tumor, arising from the epithelial component of the embryonic tooth and usually affecting the molar-ramus region of the mandible or maxilla. "Besides, “MAPK1/MAPK3 signaling” (R-HSA-5684996), “MAPK family signaling cascades” (R-HSA-5683057), “MAPK6/MAPK4 signaling” (R-HSA-5687128), and “MAPK cascade” (GO:0000165) were also dysregulated in ameloblastoma." (PMID 36160115, 2022).